HEY1 (hes related family bHLH transcription factor with YRPW motif 1)
Diseases named in the same sentence as HEY1 in open-access papers (continued):
Sharing a sentence is not in itself a finding about the gene and the disease.
glioma (13 papers, 2016 to 2023). A benign or malignant brain and spinal cord tumor that arises from glial cells (astrocytes, oligodendrocytes, ependymal cells). "Various studies have demonstrated increased expression of distinct components of Notch signaling pathway (such as Notch1, Notch2, Dll1, Dll4 and Jag1) and Notch target genes (Hey1, Hey2, Hes1) in glioma cell lines or primary human glioma samples including GBM." (PMID 36010607, 2022). "The miR-30c inhibitor enhanced the Notch1, NICD, HES1 and HEY1 proteins in A172 and U251 glioma cells, and shRNA-Notch1 weakened this enhancement." (PMID 36180477, 2022). "The retinoblastoma (pRb)/E2F cell-cycle pathway can up-regulate HEY1 expression in human glioma cells through E2F-binding sites present in its promoter, and HEY1 expression can also be induced by activation of the proto-oncogene c-Jun." (PMID 27129302, 2016). "The upregulation of Notch ligand JAG1 and targets Hey1, Hey2, Hes1 in brain tissues of glioma patients compared to that of healthy brain tissues also highlight the Notch signaling pathway as a potential therapeutic target in glioma patients." (PMID 33381038, 2020). "Interestingly, DNMT1 gene expression was increased in si-HEY1 treatment, suggesting that HEY1 can be an epigenetic target in studying glioma progression." (PMID 28574840, 2017). "The role of HEY1 in gliomas may be very closely related to its effect on LUZP2." (PMID 32695826, 2020). "When the inhibitor was transfected into glioma cells, the expression levels of the Notch1, NICD, HES1 and HEY1 proteins in the inhibitor group were significantly higher than those in the inhibitor NC group (P < 0.05)." (PMID 36180477, 2022). "Of note, since MRK003 treatment caused a severe suppression in Hes1/Hey1 expression in some of the studied cells, we acknowledge that the proposed biomarkers may only be used to monitor glioma cells ́ responsiveness to BRON, but their blockade does not explain the impaired cell invasion." (PMID 33004830, 2020). "To address if the NOTCH pathway was active in our glioma cell lines, we analyzed the gene expression profile of NOTCH receptors (NOTCH1-4), ligands (DLL 1,3,4 JAG 1,2) and target (HES1, HEY1,2) genes." (PMID 27183910, 2016). "Gliomas and medulloblastomas are the most common types of brain tumors; several studies reported that the aberration of Notch components in brain tumors, for example, the overexpression of Notch1, 3 and 4, ASCL1, and Hey1, are highly correlated with a higher grade of glioma and poor prognosis." (PMID 38201528, 2023).
osteosarcoma (13 papers, 2009 to 2025). A usually aggressive malignant bone-forming mesenchymal neoplasm, predominantly affecting adolescents and young adults. "A study found that the expressions of NOTCH1, NOTCH2, Hes1, and Hey1 increased markedly in primary canine osteosarcoma." (PMID 36975516, 2023). "Studies revealed that Notch pathway genes including Notch1, Notch2, Notch ligand DLL1, and Notch target genes including Hes-1, Hey-1, and Hey-2 were expressed in osteosarcoma cells." (PMID 34671398, 2021). "The protein expression level of HEY1 detected by western blot was consistent with the mRNA level in osteosarcoma cell lines." (PMID 32284759, 2020). "Our data also proved that HEY1 is a key factor involved in the tumorigenicity of osteosarcoma cells." (PMID 32284759, 2020). "In addition, the expression level of HEY1 was positively correlated with the tumorigenicity of osteosarcoma cell lines." (PMID 32284759, 2020). "Likewise MDM2 amplifications for the diagnosis of low-grade osteosarcoma, HEY1 fusions in case of mesenchymal chondrosarcoma and USP6 fusions in aneurysmal bone cyst." (PMID 31838586, 2020). "Herein, the tumorigenic genes in osteosarcoma cell lines were identified by bioinformatic analysis, and Hes related family bHLH transcription factor with YRPW motif 1 (HEY1) was identified as a key factor in tumorigenicity of osteosarcoma cells by subsequent experimental validation." (PMID 32284759, 2020). "Furthermore, HEY1 is a key factor in the tumorigenicity of osteosarcoma cells." (PMID 32284759, 2020). "Exosomes from human umbilical vein endothelial cells promoted the self-renewal of CSCs in osteosarcoma by enhancing the expression of NOTCH1, Hes1, and Hey1 while blocking NOTCH signaling reversed the positive effect on the CSCs." (PMID 36975516, 2023). "Expression of HEY1, HES1, and BCL11B was also increased in human mesenchymal chondrosarcoma compared with other sarcomas such as myxoid liposarcoma, Ewing sarcoma, osteosarcoma, and synovial sarcoma." (PMID 37212282, 2023). "Three of highly expressed genes (DDX10, FOXA2, and HEY1) were correlated with poor prognosis, while three of lowly expressed genes (CYP26B1, GP1BB, and IFI44) showed the opposite trend in patients with osteosarcoma." (PMID 32284759, 2020). "Another study also found that HEY1 and other downstream target genes of Notch signaling including HES1, NOTCH1 and NOTCH2, were elevated in canine osteosarcoma by gene expression microarray analysis and reverse transcriptase - quantitative PCR (RT-qPCR)." (PMID 25023069, 2014). "We found that Notch2, Jagged1, HEY1, and HEY2 were upregulated in the osteosarcoma biopsy specimens." (PMID 19455146, 2009). "In this study, we found that Notch2, Jagged1, HEY1, and HEY2 were overexpressed in human osteosarcoma specimens." (PMID 19455146, 2009). "Similarly, the expressions of NOTCH target genes (Hes1, Hes5, and Hey1, among others) in U2OS and 143B osteosarcoma cells treated with sublethal doses of cisplatin were significantly higher than those of cisplatin-sensitive cells." (PMID 36975516, 2023). "We found BMP9 up-regulates the Notch downstream target Hey1, and that BMP9-promoted proliferation and tumor growth of osteosarcoma can be effectively blunted by blocking Notch signaling, suggesting that BMP9 may function as upstream of Notch signaling." (PMID 28881833, 2017).
melanoma (12 papers, 2010 to 2025). A malignant, usually aggressive tumor composed of atypical, neoplastic melanocytes. "In previous researches, several results suggest that Hey1 promotes the invasion and metastasis of melanoma cells by regulating the GRB2/PI3K/AKT pathway." (PMID 39351154, 2024). "High-throughput RNA-sequencing analysis revealed that inhibition of Hey1 results in decreased GRB2 expression in melanoma cells." (PMID 34729100, 2021). "As the A375 cell line is widely used for melanoma investigations, it was also employed herein to examine the role of Hey1 in melanoma." (PMID 34729100, 2021). "First, bioinformatics tools, immunohistochemistry, and Western blotting analysis showed that the expression of Hey1 is increased in melanoma." (PMID 34729100, 2021). "Hey1 interference inhibited the migration and invasion of melanoma cells, while Hey1 overexpression exerted the opposite effects on melanoma cell behaviour and signaling transduction." (PMID 34729100, 2021). "In the present study, we investigated the role of Hey1 in influencing human melanoma cells and elucidated that Hey1 promotes migration and invasion of melanoma cells via the GRB2/PI3K/AKT signaling pathway." (PMID 34729100, 2021). "In conclusion, our study provides compelling evidence that Hey1 promotes melanoma cell migration and invasion through GRB2/PI3K/AKT signaling cascade." (PMID 34729100, 2021). "In the present study, we investigated the crucial role of Hey1, a target gene of Notch signaling, on the biological function of melanoma and its molecular mechanisms." (PMID 34729100, 2021). "The Hey1 mRNA expression level was significantly upregulated in melanoma tissues compared to the corresponding expression level in normal skin tissues." (PMID 34729100, 2021). "A xenograft animal model was used to study the effect of Hey1 on the growth and metastasis of melanoma cells in vivo." (PMID 34729100, 2021). "Among ErbB signaling pathway genes (Supplementary 1), we observed that the mRNA level of the adaptor protein GRB2 was significantly decreased after inhibition of Hey1 in melanoma cells, compared to that of the control." (PMID 34729100, 2021). "In summary, our results suggest that Hey1 promotes the invasion and metastasis of melanoma cells by regulating GRB2/PI3K/AKT pathway." (PMID 34729100, 2021). "Here we show that the Notch signaling downstream target Hey1 promotes migration and invasion of melanoma cells via the GRB2/PI3K/AKT pathway." (PMID 34729100, 2021). "The expression of Hey1 protein was significantly higher in melanoma cells (gll-19, mel-888, mel-624, A375, and B16) than that in the PIG1 cells." (PMID 34729100, 2021). "Then, both in vivo and in vitro experiments showed that Hey1 promotes the malignant behaviour of the melanoma cells." (PMID 34729100, 2021). "Whether it is tripartite motif-containing 14 (TRIM14)-promoted melanoma progression or Hey1-promoted melanoma invasion and migration, the PI3K/AKT pathway is an important part." (PMID 36338621, 2022). "The Hey1 expression level was higher in melanoma tissue than in normal skin tissue." (PMID 34729100, 2021). "Our results showed that Hey1 is upregulated in melanoma tissues." (PMID 34729100, 2021). "The positivity rate of Hey1 was 18% (4/22) in normal skin and 77% (21/27) in melanoma tissue." (PMID 34729100, 2021). "We found that Hey1 mediates GRB2 to regulate PI3K/AKT signaling in melanoma cells." (PMID 34729100, 2021). "Hey1 expression was first examined in normal human skin and melanoma tissues by IHC." (PMID 34729100, 2021).
melanoma (continued). "We focused our investigations on HES1 and HEY1 and not on the other existing variants, since they are the most transcribed variants in human cells and cancers and are generally the most expressed in melanoma cell lines specifically." (PMID 38705997, 2024). "However, the molecular mechanism by which Hey1 regulates melanoma cell behaviors remains largely unknown." (PMID 34729100, 2021). "Conversely, blocking Hey1 enhances TweakR–CCL2 signaling, promoting immune cell recruitment while still supporting melanoma growth and metastasis." (PMID 41465101, 2025). "A review mentioned that Notch and ERBB signaling components (i.e., Notch1, Hey1, and ERBB3) are re-expressed in melanoma in a correlative manner, and proposed that the tumorigenesis and development of melanoma require two cascade functions." (PMID 34729100, 2021). "Last, functional experiments confirmed that Hey1 positively regulates GRB2/PI3K/AKT pathway to influence migration and invasion of melanoma cells." (PMID 34729100, 2021). "Hey1 promotes the EMT process, tumor matrix metalloproteinases expression, as well as the migration and invasion of melanoma cells." (PMID 34729100, 2021). "Intriguingly, in addition to Hey1, we observed GRB2 expression was also significantly increased in the melanoma tissues compared to that of the normal skin tissues." (PMID 34729100, 2021). "The expression of the NOTCH targets HES1 and HEY1 was reduced in RO4929097-treated tumors, together with that of putative melanoma stem cell markers." (PMID 21980408, 2011). "When compared to other types of skin cancer such as basal cell carcinoma or squamous cell carcinoma, BAMBI showed selective overexpression in melanoma and strong co-expression (0.815) with the established melanoma gene EDNRB, but also with HEY1 (0.759), a gene important for vascular development." (PMID 27689402, 2016). "Additionally, HEY1, a HES-related gene that is a final effector of Notch transcriptional activity, was shown to be upregulated in melanoma cells." (PMID 24281103, 2010). "However, we propose that Hey1 may augment the expression of GRB2 to promote the invasion and metastasis of melanoma cells." (PMID 34729100, 2021). "Importantly, Notch4 may induce suppression of Snail2 and Twist1 through downstream Hey1 and Hey2 targets and is non-canonically mediated in WM9 and WM164 melanoma cell lines." (PMID 37108670, 2023).
liver cancer (10 papers, 2017 to 2026). An epithelial or non-epithelial malignant neoplasm that arises from the liver. "In addition, HEY1-related pathways modulate the cellular plasticity of liver cancer tumors, which is one of the risk factors for the disease." (PMID 34457116, 2021). "Mechanistically, USP28 interacts with HEY1 and deubiquitinates its lysine 87 residue, thereby stabilizing HEY1 and enhancing the stem-like properties of liver cancer cells." (PMID 42189121, 2026). "In this study, Se-Y significantly downregulated the expression of BMP2, FGF9, and HEY1 in the liver, indicating that it can prevent liver cancer in laying hens." (PMID 37570275, 2023). "HEY1 is associated with the occurrence of various tumours, and inhibition of HEY1 inhibits the proliferation and migration of liver cancer cells." (PMID 37570275, 2023). "NONHSAT095695.2, ENST00000552253.1 and ENST00000588495.5 regulated LDB2, which inhibits liver cancer cell proliferation and migration via suppressing the expression of HEY1." (PMID 33075110, 2020). "Furthermore, strong and growing evidence from clinical and basic research has underscored the importance of HEY1 in liver cancer development." (PMID 40507937, 2025). "Therefore, HEY1 could be an interesting clinical target for liver cancer treatment." (PMID 40507937, 2025). "The corresponding genes of middle-stage CNV events including MYC, CNBD1, HEY1, RUNX1T1, CDH17, high expression of HEY1 gene promotes self-renewal of tumor stem cells, especially in liver cancer." (PMID 34453042, 2021). "HEY1 overexpression, PINK1 down-regulation, and their correlation were also observed in intrahepatic cholangiocarcinoma (ICC), another type of primary liver cancer which is derived from bile duct." (PMID 31819034, 2019). "More strikingly, linear regression model showed that HEY1 and PINK1 mRNA expressions were reversely correlated in 72 cases of kidney cancer and non-tumorous tissues, suggesting that our findings are not restricted to liver cancers." (PMID 31819034, 2019).
ovarian carcinoma (9 papers, 2010 to 2022). A malignant neoplasm originating from the surface ovarian epithelium. "Hes1 locus is amplified in 2–25% in breast and 2–22% in ovarian cancer, followed by Hey1, Notch2 and Notch3." (PMID 31470883, 2019). "We treated Hey1 ovarian cancer cells with 1ug/mL cisplatin alone or cisplatin in combination with Ribociclib (0 nM, 250 nM, 1 uM, or 3 uM)." (PMID 29644000, 2018). "We also observed a decrease in BrdU incorporation in Hey1 ovarian cancer cells during this treatment, confirming a decrease in proliferation." (PMID 29644000, 2018). "We found that Ribociclib treatment was associated with a decrease in p-Chk1 in all tested ovarian cancer cells and in ATR in the Hey1 cell line." (PMID 29644000, 2018). "The expression of Hes1 and Hey1 also increased in galectin-3-overexpressing A2780 ovarian cancer cells." (PMID 27626163, 2016). "Over-expression of NOTCH1 intracellular domain, but not HES1 or HEY1, inhibits E-cadherin expression and induces EMT in ovarian cancer cells, probably through the induction of Snail expression." (PMID 20010940, 2010).
prostate carcinoma (9 papers, 2012 to 2025). A carcinoma that arises from epithelial cells of the prostate gland. "In prostate cancer cells HEY1 functions as a corepressor for AF1 in the AR, inhibiting transcription from androgen-dependent target genes." (PMID 33167316, 2020). "Hey1 as a co-factor of androgen receptor can inhibit androgen dependent targets, including those involved in prostate cancer progression." (PMID 28915655, 2017). "Conversely, in prostate cancer Notch can be considered a tumor suppressor particularly at the onset of tumorigenesis, when the Notch target gene Hey1 is activated." (PMID 28915655, 2017). "The luciferase activity associated with Notch target genes HES-1A/B and HEY-1 were also increased significantly upon treatment with 20 μM SFN in prostate cancer cells." (PMID 22970326, 2012). "Amongst these sets, the novel candidates KAT2A, TRIM28 and HEY1 are particularly interesting, as they represent previously unknown putative drivers of prostate cancer." (PMID 28592290, 2017). "The results were confirmed by other prostate cancer cohort (Multi-Institute, Nat Med 2016) from cBioportal which also showed the co-expression of SIRT6 and Hes1/Hey1." (PMID 33995674, 2021). "Diverse HEY1 and HES1 regulation by dihydrotestosterone was earlier observed in R1 castrate-resistant prostate cancer cell line, however the mechanism was not investigated in that study." (PMID 33167316, 2020).
colorectal cancer (8 papers, 2009 to 2024). A primary or metastatic malignant neoplasm that affects the colon or rectum. "Deregulation and aberrant expression of HEY1 have been documented in diverse malignancies, including colorectal cancer." (PMID 34422018, 2021). "Aberrant regulation of Hey1 levels through miR-769 leads to deregulation of several biological processes such as increased cell proliferation and invasion in colorectal cancers." (PMID 32211044, 2020). "Accordingly, Jagged1 expressing EC- tumor cell signaling has been described in the regulation of colorectal cancer, and in the ability of providing chemo resistance, aggressiveness to lymphoma cells by activating Notch2 and consequently Hey1 in these adjacent cells." (PMID 26213336, 2015). "Using the GWAS Catalog, we uncovered associations between HEY1 variants and various health outcomes, including educational attainment and colorectal cancer survival, though none of which overlapped with respiratory, lung function, immune function, or thyroid traits." (PMID 39237910, 2024). "Up-regulation of ZNF671 in colorectal carcinoma (CRC) cells resulted in suppressive effects on proliferative ability and metastatic potency via the deactivation of Notch signaling, with decreases in expression of Notch1, NICD, HES1 and HEY1." (PMID 39595048, 2024).